MMP9 (matrix metallopeptidase 9)
Diseases named in the same sentence as MMP9 in open-access papers (continued):
Sharing a sentence is not in itself a finding about the gene and the disease.
schizophrenia (continued). "Another study indicated that expression of the MMP-9 gene was higher and negatively related to DNA methylation in deficit schizophrenia." (PMID 38172869, 2024). "Our results demonstrated that levels of antioxidant enzymes, SOD, GSH-Px, H2O2, and MDA were significantly decreased, whereas CAT and MMP-9 levels were increased in patients with schizophrenia, when compared with healthy controls (all P < 0.05)." (PMID 38172869, 2024). "We also found that MDA levels were positively correlated with MMP-9 levels in schizophrenia patients." (PMID 38172869, 2024). "Although increasing evidence suggests that OS and MMP-9 expression levels are altered in patients with schizophrenia, the results are inconsistent." (PMID 38172869, 2024). "The present study showed that activities of Mn-SOD, CuZn-SOD, T-SOD, GSH-Px, and levels of H2O2, MDA were lower, whereas CAT activity and MMP-9 levels were higher in patients with schizophrenia than in healthy controls." (PMID 38172869, 2024). "In future research, we suggest further characterization of the relationship and mechanisms of OS and MMP-9 in the pathophysiology of schizophrenia, across both genders." (PMID 38172869, 2024). "S4B), a candidate gene for schizophrenia, which functions as an RNA binding protein to regulate Mmp-9 mRNA stabilization in hippocampal neurons for electrical activity." (PMID 36791184, 2023). "Brain-derived neurotrophic factor (BDNF), a neurotrophin, and matrix metalloproteinase 9 (MMP-9), a gelatinase B, are the promising candidate genes for schizophrenia." (PMID 36325525, 2022). "Research on human schizophrenia patientsshows that elevated MMP-9 protein levels are significantly correlated withcognitive decline, particularly in terms of language, fluency, and verbal andgeneral memory." (PMID 35061219, 2022). "In this study we suggested the implication of MMP-9 protein in the occurrence of schizophrenia following Toxoplasma infection." (PMID 32460746, 2020). "Although the implication of MMP-9 in schizophrenia onset was studied, possible implication of MMP-91562 C/T gene polymorphism is still to be clarified." (PMID 32460746, 2020). "An unbiased approach in screening altered levels of plasma proteins in patients with schizophrenia also revealed increased levels of MMP-9 and TIMP-1." (PMID 31172215, 2019). "Another independent study confirmed increased MMP-9 activity in the blood of schizophrenia patients." (PMID 31172215, 2019). "Increased MMP-9 serum levels were likewise found to be correlated to oxidative stress in schizophrenia cases." (PMID 31172215, 2019). "Recent studies of MMP-9 gene polymorphisms and MMP-9 mRNA and protein levels have implicated MMP-9 in schizophrenia patients." (PMID 31555105, 2019). "Our analyses placed LOX at the centre of ECM remodelling networks that are associated with BD, schizophrenia and AD, involving Elastin, which is the direct target of LOX, together with TGF-β1 and MMP9." (PMID 31477687, 2019). "Recent studies have hinted at the potential role of MMP-9 in the manifestation of schizophrenia phenotypes." (PMID 30123106, 2018). "Aberrant levels of MMP-9 has been observed in different psychiatric disorders, including schizophrenia and importantly, blood levels of MMP-9 or gene responsiveness to antipsychotics has been related to this disorder." (PMID 29755331, 2018). "These animals exhibited a decrease in MMP‐9 levels in the brain and were more sensitive to MK‐801‐induced locomotor hyperactivity, a model of the positive symptoms of schizophrenia." (PMID 28623238, 2017). "A positive correlation was also shown between serum levels of MMP-9 and the lipid peroxidation marker malondialdehyde in individuals with schizophrenia." (PMID 28588507, 2017).
schizophrenia (continued). "We propose an alternative function for MMP‐9 in the pathophysiological underpinnings of schizophrenia, by pointing to a novel mechanism that involves changes in MMP‐9 levels at the excitatory synapse and MMP‐9‐dependent changes in dendritic spine morphology." (PMID 28623238, 2017). "Cumulative evidence suggests that serum levels and activity of MMP-9 are increased in schizophrenia individuals compared with healthy controls." (PMID 28588507, 2017). "In fact, our results suggest that MMP‐9 contributes to an important biological subgroup under the heterogeneous “umbrella diagnosis” of schizophrenia." (PMID 28623238, 2017). "Our data for the MMP‐9 rs20544 C/T SNP showed that C carriers (CC/CT) exhibited more severe positive symptoms of schizophrenia than TT carriers." (PMID 28623238, 2017). "MMP-9 influences synaptic plasticity, thought to be relevant to the neurobiology of schizophrenia possibly by converting pro-brain-derived neurotrophic factor (BDNF) to BDNF." (PMID 28588507, 2017). "Isoacteoside (mol43) targeted MMP9, is an important player in central nervous system and would be a putative mediating enzyme for neuropsychiatric disorders such as schizophrenia and bipolar illness." (PMID 29180652, 2017). "In drug-free patients with schizophrenia, MMP-9 levels were higher comparing to controls; moreover, previous use of antipsychotics was associated with higher concentrations of MMP-9." (PMID 27409603, 2016). "Recent data suggest involvement of MMP-9 in disturbed synaptic plasticity and morphology of spines in schizophrenia, bipolar disorder and alcohol dependency." (PMID 27409603, 2016). "In groups with resistant schizophrenia with ongoing clozapine treatment, levels of MMP-9 were higher comparing to healthy controls." (PMID 27409603, 2016). "Our project is the first randomized placebo-controlled study to investigate the sarcosine (or glutamatergic agent in general) effects on MMP-9 serum levels in individuals with schizophrenia." (PMID 27409603, 2016). "Despite established involvement of MMP-9 in basic cognitive processes, the literature concerning the potential reciprocal relation between this metalloproteinase and schizophrenia is very sparse." (PMID 27409603, 2016). "Initial serum MMP-9 concentrations cannot be used as a predictor of the improvement resulting from sarcosine addition in patients with schizophrenia in stable mental condition." (PMID 27409603, 2016). "MMP-9 levels are also increased in patients with schizophrenia, and dendritic spine alterations have been identified in multiple brain regions in schizophrenia." (PMID 25071472, 2014). "Since MMP9 influences hippocampal and prefrontal cortical activity, we hypothesized that a polymorphism of the MMP9 gene is associated with the pathogenesis of schizophrenia, a condition in which prefrontal cortex impairment is one of the most common pathological findings." (PMID 20037727, 2009). "The secretion and maturation of pro-inflammatory cytokines, such as IL1b and TNFa, in schizophrenia (SCZ) may be facilitated by MMP-9." (PMID 38254696, 2024). "Accumulating evidence has indicated that oxidative stress (OS) and matrix metalloproteinase-9 (MMP-9) may contribute to the mechanism of schizophrenia." (PMID 38172869, 2024). "Moreover, in a mouse model of redox dysregulation relevant to schizophrenia, MMP-9 induced a feedforward loop between oxidative stress and neuroinflammation, leading to interneuron maturation impairments." (PMID 38431757, 2024). "MMP-9 influences the function of the hippocampus and the prefrontal cortex, and as a consequence it is suspected of being involved in the development of schizophrenia (SZ), in which damage to the prefrontal cortex is one of the most common pathological symptoms." (PMID 37206663, 2023).
schizophrenia (continued). "BDNF rs6265 196 G > A and MMP-9 rs3918242–1562C > T SNPs are related to the clinical features of schizophrenia and could be a useful biomarker for the changes, remission or deterioration of clinical status of schizophrenia." (PMID 36325525, 2022). "A human study conducted postmortem in patients affected by ASD and schizophrenia showed increased expression of two markers of neuroinflammation and blood–brain barrier impairment, matrix metallopeptidase 9 (MMP9) and 18 kDa translocator protein (TSPO), in the cerebral cortex." (PMID 34886561, 2021). "The present study showed that stress exacerbated schizophrenia-like symptoms in mice that had low MMP-9 levels, thus supporting the hypothesis of the involvement of MMP-9 in schizophrenia and suggesting a possible pharmacological treatment target." (PMID 31555105, 2019). "MMP9 has been considered to have pathological importance in patients with schizophrenia." (PMID 30619470, 2018). "Matrix metalloproteinase 9 (MMP9) might be associated with neural plasticity and glutamate regulation, involved in schizophrenia pathogenesis." (PMID 30619470, 2018). "Clearly additional studies are needed to test whether elevated MMP-9 levels do indeed drive PNN changes observed in prefrontal cortex of schizophrenia mouse models and how it relates to the human condition." (PMID 30123106, 2018). "One of the ECM modifying enzymes, MMP-9, has been hypothesized to play a role in pathophysiology of schizophrenia, AD and FXS." (PMID 30123106, 2018). "In summary, the present study provided evidence for abnormal peripheral gene expression and DNA methylation of MMP9 in DS patients, indicating that subjects with the deficit syndrome might be a specific sub-group within schizophrenia." (PMID 30619470, 2018). "Previous reports on MMP9 in patients with schizophrenia are inconsistent." (PMID 30619470, 2018). "However, several previous reports have also demonstrated that MMP9 expression is substantially altered in peripheral blood in patients with schizophrenia." (PMID 30619470, 2018). "The present study demonstrated hypo-methylation status in exon 4 and exon 5 of MMP9 in two schizophrenia subgroups compared to health controls, which might result in up-regulated gene expression of MMP9." (PMID 30619470, 2018). "We report here that MMP‐9 3′UTR gene polymorphism does not increase the general risk of schizophrenia, but it contributes significantly to the chronic delusional syndrome in schizophrenia patients." (PMID 28623238, 2017). "In conclusion, we found a specific association between a molecular mechanism that involves synaptic MMP‐9 and a biological subgroup of schizophrenia, which may open new avenues for individualized treatment of this devastating disease in the future." (PMID 28623238, 2017). "Interestingly, another MMP‐9 SNP −1562C/T (rs3918242) has also been shown to affect PANSS score in schizophrenia patients." (PMID 28623238, 2017). "In conclusion, we found a specific association between a molecular mechanism that involves synaptic MMP‐9 and a biological subgroup of schizophrenia, which may open new avenues for individualized treatment of this devastating disease." (PMID 28623238, 2017). "Our case–control results demonstrate that MMP‐9 rs20544 per se is not a risk SNP for a schizophrenia endpoint diagnosis, but schizophrenia individuals who carry the C allele (CC/CT) are more severely affected by chronic delusions compared with TT carriers." (PMID 28623238, 2017). "Furthermore, MMP‐9 mRNA levels were strikingly upregulated in blood cells in treatment‐naive schizophrenia patients to decline after antipsychotic treatment." (PMID 28623238, 2017). "To search for potential behavioral consequences of MMP‐9 rs20544 variants, we conducted a phenotype‐based genetic association study (PGAS) in schizophrenia patients from the Göttingen Research Association for Schizophrenia (GRAS) data collection." (PMID 28623238, 2017).
schizophrenia (continued). "Furthermore, similar to schizophrenia and autism, increased levels of MMP-9 have been reported in blood samples from subjects with major depression and young subjects with bipolar disorder in a depressed state." (PMID 26839720, 2016). "The possibility that MMP-9, as well as other MMPs with potentially related functions, may represent genetic vulnerabilities in schizophrenia has been gaining evidence in recent times." (PMID 26839720, 2016). "Genetic studies also indicate involvement of MMP-9 in pathogenesis of schizophrenia." (PMID 27409603, 2016). "Considering the involvement of both MMP-9 and glutamate in synaptic plasticity, memory and other cognitive processes impaired in schizophrenia, we hypothesize the relationship between MMP-9 levels and psychopathology changes induced by sarcosine." (PMID 27409603, 2016). "Recently, MMP-9 has been implicated in several psychiatric disorders that are associated with abnormal development including FXS, autism spectrum disorder (ASD), bipolar disorder and schizophrenia." (PMID 26283917, 2015). "It was also found that in pathological conditions abnormal MMP-9 release contributes to the development or influences the course of many brain disorders, including epilepsy, autism spectrum disorders, brain strokes, brain tumors, neurodegeneration, brain injuries, schizophrenia, and alcoholism." (PMID 37206663, 2023). "Based on the data of this study, and in line with previous findings, MMP-9 1562 C/C genotype was considered as an independent predictor of the severity and was assessed by the positive and negative syndrome scale (PANSS), affirming association between MMP-9 genotypes and schizophrenia." (PMID 36325525, 2022). "Thus, treatment with this drug could be considered in cases of schizophrenia patients who have specific MMP-9 gene variations." (PMID 31555105, 2019). "Thus, stressed Mmp-9 heterozygous mice might serve as a useful model of the deficit type of schizophrenia." (PMID 31555105, 2019). "The main limitation was that MMP9 DNA methylation and gene expression were detected in PBMCs, where MMP9 expression and methylation may not necessarily represent that occurring in brain regions relevant to the pathogenesis of schizophrenia." (PMID 30619470, 2018). "The present study employed different methodologies (e.g., MMP9 expression and methylation) to study deficit and non-deficit subtypes and further demonstrated the association between elevated gene expression of MMP9 and negative symptoms of schizophrenia." (PMID 30619470, 2018). "The social amotivation factor of SANS would represent the behavioral abnormality relevant to the learning disability of social experiences and adaptive exchanges, consistent with the hypothesis that MMP9 contributes to pathological synaptic plasticity in schizophrenia." (PMID 30619470, 2018). "MMP9 is synthesized by neurons, astrocytes and microglia in hippocampal and prefrontal cortex, which are the critical brain regions associated with negative symptoms in schizophrenia." (PMID 30619470, 2018). "Locomotor hyperactivity in Mmp‐9 heterozygous mice, which have lower levels of Mmp‐9 expression in the brain, together with decreased MMP‐9 activity for the “risk” MMP‐9_C variant supports the previously postulated connections between MMP‐9 activity, glutamate signaling, and schizophrenia." (PMID 28623238, 2017). "Genetic studies have also suggested that MMP-9 may contribute to the pathology of schizophrenia." (PMID 28588507, 2017). "A link between a key regulator of dendritic spines’ (small dendritic protrusions that harbor excitatory synapses) plasticity, MMP‐9 (matrix metalloproteinase), and schizophrenia has been postulated, but no explanation of the underlying molecular mechanisms has been previously provided." (PMID 28623238, 2017).
schizophrenia (continued). "Therefore, we conclude that there is need for further studies, in which assessment of MMP-9 levels will be performed in particular brain regions particularly important in schizophrenia, such as dorsolateral prefrontal cortex, anterior cingulate cortex or hippocampus." (PMID 27409603, 2016). "These biomarkers are associated with lower prefrontal gamma-aminobutyric acid (GABA) levels, further supporting the link between MMP9/RAGE pathway activation, inhibitory and excitatory imbalances, and the clinical manifestations of schizophrenia." (PMID 40650013, 2025). "A case control study also reported that serum MMP-9 was correlated with MDA and total antioxidant status in drug-free male schizophrenia." (PMID 38172869, 2024). "However, it is unclear whether MMP9 expression might be associated with epigenetic changes that potentially influence negative symptoms in schizophrenia." (PMID 30619470, 2018). "Beside its antibiotic activity, minocycline can reduce plasma levels of MMP-9 and inhibit MMP-9 activity, suggesting a possible role of MMP-9 inhibition in the beneficial effects of minocycline in schizophrenia." (PMID 30123106, 2018). "Since FMRP negatively regulates MMP‐9 mRNA translation and the variant resulting in lower MMP‐9 activity at the spines (CC/CT) is the “risk” variant, one could speculate that the downregulation of FMRP in schizophrenia is even a compensatory mechanism to overcome decreased MMP‐9 levels." (PMID 28623238, 2017). "In fact, in Rahimi’s study, MMP-9 and TIMP-1 are involved in neurotransmission processes and are strong candidates for the appearance of positive symptoms and negative symptoms, as well as cognitive dysfunction typical of schizophrenia." (PMID 38254696, 2024). "In certain cases, research studies focused on schizophrenia have shown that there are no notable variations in the expression of MMP-9 in blood samples collected from individuals diagnosed with SCZ compared to those without the condition." (PMID 38254696, 2024). "A previous study reported that serum MMP-9 levels neither differed significantly between patients with schizophrenia and healthy controls nor correlated with disease severity." (PMID 38172869, 2024). "Another important inference in this cluster is related to biomarkers for schizophrenia that include peripheral (BDNF/neurotrophic factor, matrix metallopeptidase 9 (MMP-9), cytokine, oxidative stress) and neuroimaging (magnetic resonance imaging (MRI), cortical thickness) biomarkers." (PMID 37077958, 2023). "A previous study reported increased MMP9-induced shedding and activation of RAGE, which mediated neuroinflammation and the reduction of perineuronal nets (PNNs) in the anterior cingulate cortex in schizophrenia mice models." (PMID 34020590, 2021). "This study explores gene expression and DNA methylation of MMP9 in peripheral blood mononuclear cells (PBMCs) and their relationship with clinical symptoms in DS and non-deficit schizophrenia (NDS)." (PMID 30619470, 2018). "Recent studies indicate that minocycline administration may reverse both schizophrenia and FXS phenotypes, perhaps due to its ability to lower MMP-9 levels or activity." (PMID 30123106, 2018). "As there is evidence for abnormal MMP-9 regulation in FXS, schizophrenia and AD as well as altered PNNs in presbycusis and acoustic trauma models, studies of how MMP-9 is involved in PNN regulation are crucial for the development and validation of future therapeutics." (PMID 30123106, 2018). "The well‐established role of MMP‐9 in regulating NMDA signaling, dendritic spine morphology, and prefrontal and hippocampal function has drawn attention to the potential involvement of MMP‐9 in the development of schizophrenia." (PMID 28623238, 2017). "On the other hand, we obtained strong evidence showing that two other schizophrenia-related genes, MMP9 and TGFB1, were not significantly altered according to the analysis of our PCR arrays." (PMID 29302405, 2017).